GLS (glutaminase)
Diseases named in the same sentence as GLS in open-access papers (continued):
Sharing a sentence is not in itself a finding about the gene and the disease.
breast carcinoma (continued). "Taken together, these findings demonstrate that GLS inhibition leads to the induction in ISR pathway activity in breast cancer cell lines." (PMID 28950000, 2017). "This study has identified GLS a potential therapeutic target in breast cancer, specifically in the basal subtype that exhibits a deregulated glutaminolysis pathway." (PMID 28950000, 2017). "GLS has also been shown to be a direct effector of RHO-mediated transformation of breast cancer cells." (PMID 28950000, 2017). "On the other hand, BPTES and its more potent analog CB-839 demonstrated the expected pharmacodynamic (PD) modulation, growth inhibition, and rescue phenotype by αKG in GLS dependent breast cancer cells." (PMID 28950000, 2017). "Lastly, we demonstrated that simultaneous inhibition of GLS and mTOR is synergistic in responder lines signifying a novel combination approach for the development of GLS inhibitors in basal-type breast cancers." (PMID 28950000, 2017). "Upon treatment of breast cancer cell lines with GLS inhibitor CB-839, there was a decrease in the levels of phospho-P70 S6K (Thr 389) in the responder cell lines only." (PMID 28950000, 2017). "For these experiments, we used MDA-MB-231 breast cancer cells, which have high endogenous levels of both GLS and c-Jun." (PMID 27089238, 2016). "Using the MDA-MB-468 breast cancer cell line, which exhibits relatively low endogenous levels of c-Jun and moderate levels of GLS, we generated derivative cell lines that stably overexpress JUN-V5 or carry the empty plasmid vector." (PMID 27089238, 2016). "We also found that in human breast cancer cell lines, c-Jun levels correlate strongly with GLS levels and with sensitivity to the GLS inhibitor BPTES." (PMID 27089238, 2016). "Here we show that the oncogenic transcription factor c-Jun is essential for this signalling outcome, and also acts as a primary regulator of GLS expression in human breast cancer cells." (PMID 27089238, 2016). "In human breast cancer cells, GLS protein levels and sensitivity to GLS inhibition correlate strongly with c-Jun levels." (PMID 27089238, 2016). "Here, the authors show that overexpression of the JUN proto-oncogene in breast cancer cells regulates glutaminase expression and is sufficient to confer sensitivity to glutaminase-targeted therapy." (PMID 27089238, 2016). "KGA is up-regulated in tumors from diverse organs and cells including breast, lung, liver, brain and B cells, while GAC is predominantly expressed in human breast cancer cell line that exhibits a high rate of glutamine utilization and GLS activity." (PMID 26402672, 2015). "Glutamine synthetase also represses glutaminase and contributes to the maintenance of the polarized expression of glutamine synthetase and glutaminase among breast cancer cells." (PMID 21852960, 2011). "The expression of GLUL and GLS are inversely correlated in the luminal and basal types of primary breast cancers, cancer cell lines, and primary epithelial cells." (PMID 21852960, 2011). "For example, the higher GLS level and sensitivity to glutamine deprivation of basal-type breast cancer cells are consistent with a high level of c-myc activity in basal cells and the recently described role of c-myc in regulating GLS." (PMID 21852960, 2011). "There was little effect of GLS inhibition using CB-839 in luminal breast cancer." (PMID 41898641, 2026). "Indeed, BPTES treatment reduced in a dose-dependent manner cell viability, highlighting the critical role of glutaminase in the aberrant survival of breast cancer cells." (PMID 40114244, 2025). "Breast tumor organoids derived from three independent triple negative breast cancer patients (T3N0 grade 3, T2N3 grade 3, T4N2a grade 3) were assessed for endogenous expression of circPVT1, miR-33a-5p, MYC and GLS which resulted comparable to that of the originating breast cancer tissues." (PMID 40114244, 2025). "The expression of GLS isoforms in breast cancer can be regulated by different genes." (PMID 39973065, 2025).
breast carcinoma (continued). "Collectively, these findings indicate that aberrant expression of circPVT1 might contribute to glutamine addiction of breast cancer cells leading to the aberrant activation of glutaminase." (PMID 40114244, 2025). "GLS, YY1AP1, FBXO22, KLC1, CUL4A, KITLG, and CYRIB are changed by AS that may be linked to the emergence of breast cancer." (PMID 40384436, 2025). "Indirectly, oncogenic Rho GTPase signaling activates JNK (c-Jun N-terminal kinase), which phosphorylates and stabilizes c-Jun, forming a coherent JNK/c–Jun/GLS promoter axis that amplifies GLS expression and promotes glutamine metabolism in breast cancer cells." (PMID 41179661, 2025). "Furthermore, we show that combining chemical inhibition of GLS with ELAVL1 silencing synergistically decreases breast cancer cell growth and invasion." (PMID 38965208, 2024). "FDX1 (P < 1E‐12), LIAS (P = 2.22E‐16), LIPT1 (P < 1E‐12), DLD (P < 5.46E‐09), DLAT (P = 3.14E‐02), PDHA1 (P = 1.15E‐07), MTF1 (P = 1.07E‐09), and GLS (P = 2.48E‐05) were downregulated in breast cancer, while PDHB (P = 5.04E‐07) and CDKN2A (P = 1.62E‐12) were upregulated." (PMID 39432636, 2024). "Finally, we show that combining ELAVL1 silencing with glutaminase inhibition further impairs breast cancer cell growth, migration, and invasion." (PMID 38965208, 2024). "We propose that double targeting of glutaminase and HuR may have a therapeutic benefit for treating breast cancer." (PMID 38965208, 2024). "Increases in GLS expression and its specific activity have been implicated in several human cancers, although GLS2 has also been shown to be important in luminal-subtype breast cancer." (PMID 39662828, 2024). "Interestingly, recent studies underscore the important role of glutaminase in the aggressive subgroup of luminal breast cancer and in progression from luminal DCIS to invasive cancer." (PMID 36831625, 2023). "Furthermore, GLS2 that is upregulated by GATA3 in luminal-subtype breast cancer modulated the resistance to GLS inhibitors such as BPTES." (PMID 37249801, 2023). "In breast cancer, GLS and GLS2 are overexpressed at distinct levels depending on the histological subtype, and cells may display dependency on glutamine to survive, GLS2 being investigated as a protumorigenic gene." (PMID 37685021, 2023). "Studies have shown that the expression of GLS in some breast cancer and nervous system tumors is higher than that in normal tissues, and the use of small molecule GLS inhibitors such as BPTES, CB-839 and compound 968 can significantly inhibit the growth of tumor cells." (PMID 35310969, 2022). "In breast cancer, stabilization of mitochondrial glutaminase (GLS) by SIRT5-mediated desuccinylation leads to enhanced proliferation and survival, serving substrates for numerous metabolic pathways, correlating to poorer breast cancer prognosis when found overexpressed." (PMID 35328633, 2022). "One key finding reported in the present study is the unexpected decrease of GLS protein levels in FAHD1‐depleted breast cancer cells, which may have widespread consequences for the metabolic state of these cells." (PMID 35962472, 2022). "Furthermore, GLS2 has been reported to be a critical glutaminase isozyme in luminal‐subtype breast cancer." (PMID 35538890, 2022). "For example, breast cancer has been well studied in which glutamate overproduction by enhanced glutaminase is released via the system xCT to activate mGluR3 signaling to increase invasiveness, and xCT inhibition with sulfasalazine decreases breast tumor growth." (PMID 36457557, 2022). "In addition, GLS inhibitors have also been found to inhibit growth and migration of myofibroblastic hepatic stellate cells, while glutaminase inhibition has been reported to reduce cell growth in breast cancer cells." (PMID 33718214, 2021).
breast carcinoma (continued). "Glutamine metabolism affected histone modifications in human breast cancer cell lines, and the treatment of non-invasive epitelial and invasive mesenchymal breast cancer cell lines with a glutaminase inhibitor induce a downregulation of epigenetic regulatory genes, such as Sirt1." (PMID 34026764, 2021). "High Glutaminase (GLS1) expression may have prognostic implications in colorectal and breast cancers; however, high quality data for expression in prostate cancer (PCa) are lacking." (PMID 33947068, 2021). "Application of a pan-glutaminase inhibitor 968 suppresses BPTES-resistant breast cancer growth." (PMID 33194749, 2020). "Moreover, SIRT5 desuccinylates glutaminase (GLS) and suppresses the activity of GLS to reduce ammonia production in human breast cancer cells MDA-MB-231 and mouse myoblast cells C2C12." (PMID 30759120, 2019). "The effect of glutaminase inhibition in two breast cancer patient-derived xenograft (PDX) models." (PMID 31088535, 2019). "GLS protein levels in breast cancers patient tumors significantly correlated with increased tumor grade and stage confirming the role of increased glutamine metabolism in aggressive breast cancers." (PMID 31428575, 2019). "Our analysis of the cellular responses to either GLS knockdown or pharmacological inhibition has identified potential PD markers and provides a molecular basis for combining GLS and mTOR inhibitors as a novel therapeutic strategy for treating basal breast cancers." (PMID 28950000, 2017). "Moreover, we demonstrate that overexpression of the JUN proto-oncogene is sufficient to sensitize breast cancer cells to glutaminase-targeted therapy." (PMID 27089238, 2016). "Moreover, we show that the c-Jun transcription factor is an important regulator of GLS expression in breast cancer, and can drive cellular dependence on the glutaminase reaction, thus conferring sensitivity to the GLS inhibitor BPTES." (PMID 27089238, 2016). "However, recently a small molecule inhibitor was shown to target GLS (kidney-type glutaminase) and to have antiproliferative activity in breast cancer cells while being unharmful to normal cells." (PMID 22823888, 2012). "As glutaminase inhibitors have recently become clinically available for a variety of cancers and chronic conditions, study findings encourage further exploration of these inhibitors as potential therapies targeting metabolic flexibility, including glucose metabolism, in breast cancer." (PMID 40075737, 2025). "Furthermore, high protein expression of glutamine-prolinases (GLS, ALDH18A1 and P5CR) is associated with high c-Myc protein expression in only luminal B breast cancer, suggesting that c-Myc is the driving force behind the metabolic state of the breast cancer subclass." (PMID 39051546, 2024). "Therefore, also for breast cancer, L-ASNases with low glutaminase co-activity may allow decreased toxicity and prolonged treatment." (PMID 35205650, 2022). "However, whether GLS inhibition can reverse ADR resistance in ADR-resistant breast cancer cells remains unknown." (PMID 34354052, 2021). "Moreover, targeting GLS and mTOR in advanced breast cancer may be a novel therapeutic approach in advanced ER+ breast cancer." (PMID 31428575, 2019). "Since c-Jun directly binds the promoter of the GLS gene, and endogenous levels of c-Jun and GLS correlate strongly in human breast cancer cell lines, we determined whether inhibition of JNK, inhibition of AP-1 family transcription factors, or knockdowns of c-Jun, affected GLS levels in these cells." (PMID 27089238, 2016). "Recent studies have suggested that glutamine and GLS1 activity are required for optimal growth of breast cancer cell lines in vitro and in vivo and additional work will clarify whether mesenchymal markers predict sensitivities to GLS inhibition in this population." (PMID 25502225, 2014). "A therapeutic strategy that involves dual inhibition of GLS and HUR has been proposed as a treatment for breast cancer." (PMID 40598593, 2025).
breast carcinoma (continued). "Dual inhibition of glutaminase and CPT significantly disrupts the energy supply of breast cancer cells, providing therapeutic relevance for managing drug-resistant cases." (PMID 40002245, 2025). "In drug-resistant breast cancer MYC is overexpressed, glutamine transporter proteins SLC1A5 and GLS are upregulated, and glutamate metabolism is markedly enhanced to promote proliferation of drug-resistant tumor cells." (PMID 39027328, 2024). "To confirm that HuR impacts GLS isoforms, both at the protein and mRNA levels, we knocked down ELAVL1 in 6 breast cancer cell lines (SKBR3, BT549, MDA-MB-231, MDA-MB-157, HCC38, and Hs578t)." (PMID 38965208, 2024). "One study also reported that metformin inhibits tumorigenesis by inhibiting glutaminase, and prolonged treatment with metformin decreased L-glutamate accumulation in MDA-MB-231 breast cancer cell lines." (PMID 39767805, 2024). "Compared with other subtypes of breast cancer, TNBC is characterized by the overexpression of glutaminase (GLS), which results in an increased rate of glutamine metabolism." (PMID 37731509, 2023). "There is growing evidence that glutaminase (GLS), a key enzyme that regulates the metabolism of glutamine, is significantly up-regulated in breast cancer cells, resulting in excessive utilization of glutamine in breast cancer cells." (PMID 37120513, 2023). "This compound showed anti-proliferative activity in several breast cancer cell lines, including DU4475 cells that display intrinsic resistance to BPTES, a selective GLS inhibitor." (PMID 38067269, 2023). "CB-839, a GLS inhibitor, is regarded as a putative treatment for tamoxifen-resistant LCC9 breast cancer cells and UECC." (PMID 36077501, 2022). "AI-resistant breast cancer cells show significant upregulation of the glutamine transporters SLC1A5 and GLS, and inhibition of MYC, SLC1A5, and GLS decrease cell proliferation in AI-resistant cells." (PMID 36059650, 2022). "In breast cancer cells, sirtuin-5 (SIRT5), a mitochondrial NAD+-dependent lysine deacylase, was shown to stabilize GLS by desuccinylating GLS and preventing it from ubiquitin-mediated degradation." (PMID 36139432, 2022). "In HER-2+ breast cancer, NF-κB was proven to be essential in the HER2-stimulated glutaminase expression, which is a rate-limiting enzyme involved in the metabolism of glutamine and its conversion to glutamate, leading to ATP provision and anabolic processes." (PMID 33266219, 2020). "This work demonstrates that the glutaminase inhibitor CB-839, which currently is in early clinical trials for TNBC patients, significantly inhibits tumor growth in one of the breast cancer PDX models, the luminal b/ER+ MAS98.06 model." (PMID 31088535, 2019). "Combination of everolimus and CB-839, an inhibitor of glutaminase (GLS), attenuates the growth of endocrine resistant human breast cancer xenografts." (PMID 31428575, 2019). "Knocking down of GLS gene in the mouse mammary tumor cells, the MCF-7 breast cancer cells, and glioblastoma cells led to a reversion of the transformed phenotype." (PMID 24096582, 2014). "In summary, when glutamine and glucose are abundant, MYC promotes their uptake and uniquely controls GLS and GLUL expression in antiestrogen resistant breast cancer cells." (PMID 25339305, 2014). "Using tissue microarray sections generated from 740 cases of breast cancer, we performed immunohistochemical staining for Glut-1, CAIX, MCT4, ATP synthase, glutaminase, BNIP3, Beclin-1, LC3A, LC3B and p62." (PMID 24020991, 2013). "Klebsiella pneumoniae glutaminase was able to reduce the viability of HeLa cells in a dose-dependent manner, with an IC50 value of 305.78 μg/ml in human hepatocellular carcinoma and an IC50 value of 400.51 μg/ml in breast cancer cell lines." (PMID 39905290, 2025).
breast carcinoma (continued). "Abril and coworkers developed a small molecule inhibitor of SIRT5 called DK1-04e that inhibited the metastatic properties of breast cancer cells through desuccinylation of various metabolic enzymes, e.g., IDH, GLS, SHMT2, and PKM2, and significantly impaired tumor growth in experimental mice." (PMID 39781339, 2025). "The overexpression of glutaminase (GLS), the enzyme that generates glutamate from glutamine, makes TNBC more glutamine-reliant and sensitive to glutaminolysis-targeting therapies than other breast cancer subtypes." (PMID 38672570, 2024). "However, another GLS inhibitor, the small molecule 968, can suppress GLS2 effectively and inhibit cell growth and proliferation in BPTES-resistant breast cancer." (PMID 37249801, 2023). "Drug metabolism associated studies have shown that CB-839 inhibits the activity of GLS, thereby restricting glutamine derivatives from entering the TCA cycle, so it has a significant inhibitory effect on the growth of breast cancer, soft tissue sarcoma and other malignant cells." (PMID 35310969, 2022). "Additionally, it was discovered via research of the impact of gene expression patterns on overall survival in breast cancer that those expressing high levels of ATP7A, DBT, DLAT, DLD, GLS, PDHA1, and SLC31A1 had a bad prognosis." (PMID 36059516, 2022). "The use of the glutaminase inhibitor, CB-839, in combination with the CDK4/6 inhibitor, palbociclib, resulted in blocking cell cycle progression and improved anti-tumor activity in ER+ breast cancer." (PMID 34638293, 2021). "Importantly, GLS inhibitors are previously reported to suppress the EMT traits in lung and breast cancer cells." (PMID 34168290, 2021). "However, the pan-glutaminase inhibitor compound 968 targets protein forms of both GLS1 and GLS2 (LGA) and has recently been utilized to suppress luminal-type breast cancer growth by inhibiting the previously underappreciated LGA." (PMID 32937954, 2020). "The glutamine metabolism-related proteins, such as GLS-1, glutamate dehydrogenase (GDH), and ASCT2 were found to be highly expressed in HER2-positive breast cancer than other subtypes, which indicated that HER2-positive breast cancer had the highest glutamine metabolism activity." (PMID 33489906, 2020). "Among all breast cancer subtypes, HER2-positive tumors show the highest expression of glutaminase (GLS) and glutamate dehydrogenase (GDH) and overexpression of HER2 in a cell line model directly increases GLS expression." (PMID 29930756, 2018). "Glutaminase inhibitors have already been used successfully in preclinical studies inhibiting the proliferation of TNBC but not of ER+ breast cancer cell lines." (PMID 27590516, 2016). "This could explain why TNBC cell lines have higher GLS levels and greater sensitivity to the GLS inhibitor CB-839 (a BPTES derivative) than receptor-positive breast cancer cells." (PMID 27089238, 2016). "Glutamate secretion in cancer cells is affected by the extracellular concentration of cystine, and intracellular glutaminase activity does not correlate with glutamine consumption in breast cancer cells." (PMID 25670024, 2015). "While in prostate cancer cells, MYC knockdown was shown to decrease GLS and increase GLUL protein levels, in our antiestrogen resistant breast cancer cell models (LCC9, LCC2, and LY2) we observed the reverse effect – MYC knockdown increased GLS and decreased GLUL protein levels." (PMID 25339305, 2014). "MYC regulation of GLS and GLUL in antiestrogen resistant breast cancer cells was unexpected." (PMID 25339305, 2014). "We next examined whether the expression patterns of GLUL, GLS and GLS2 found in luminal and basal cell lines were also reflected in the respective subtypes of primary human breast cancers." (PMID 21852960, 2011).